FCGR2A (Fc gamma receptor IIa)
Diseases named in the same sentence as FCGR2A in open-access papers (continued):
Sharing a sentence is not in itself a finding about the gene and the disease.
malaria (continued). "In addition to these, we genotyped the coding variants FCGR2A/rs1801274 and FCGR2B/rs1050501 in 234 individuals from a malaria-endemic area in Burkina Faso." (PMID 37958695, 2023). "Individuals of the Ewe ethnic group showed a reduced risk to clinical malaria compared to other ethnic groups, however, the distribution of genotypes was not different between the ethnic groups except for FCGR2A-497A>G and FCGR3B-194A>G." (PMID 23049979, 2012). "TLR9 T1237C seems to condition susceptibility to malaria in Burundian children but not its severity, whereas none of the assessed SNPs of TLR4, TIRAP and FCGR2A seem to influence susceptibility to malaria and disease severity in this population." (PMID 22691414, 2012). "The overall data seem to indicate that none of the SNPs of TLR4, TIRAP and FCGR2A genes studied, assessed in Burundian children, play a role in modulating susceptibility to malaria and disease severity in this population." (PMID 22691414, 2012). "Genetic polymorphisms present in FCGR2A and FCGR3B genes could alter the affinity of FcgRIIA and FcgRIIIB receptors for IgG, and therefore, influence the quality of the immune response against malaria." (PMID 36499205, 2022). "Five TNF enhancer SNPs and the FCGR2A R131H (G/A) SNP were analyzed for association with severity of P. falciparum malaria in a malaria-endemic and a non-endemic region of India in a case-control study with ethnically-matched controls enrolled from both regions." (PMID 18194515, 2008).
COVID-19 (16 papers, 2020 to 2025). A disease caused by infection with severe acute respiratory syndrome coronavirus 2. "FCGR2A polymorphisms have been associated with the risk of developing autoimmune diseases and the extent of viral disease, including COVID-19." (PMID 38602517, 2024). "We found that the frequency of intron variants rs72717040 and rs17400517 of FCGR2A correlated with the frequency of COVID-19." (PMID 33981715, 2021). "We also investigated whether these GM alleles synergistically/epistatically with IGHG3 and FCGR2A alleles—which have been previously implicated in COVID-19—modulated the extent of COVID-19 severity." (PMID 38602517, 2024). "Finally, for the genes GYPB and FCGR2A, further investigations are needed to confirm an association with COVID-19 along with molecular studies to shed light on the mechanisms responsible for higher/lower incidence of SARS-CoV-2 infections." (PMID 33981715, 2021). "Thromboembolic events are an important cause of death in critically ill patients with COVID-19, and platelet-mediated immune thrombosis within the plasma of COVID-19 patients can be reversed by blocking FCGR2A-Syk pathway signaling on platelets." (PMID 38674681, 2024). "Due to the pivotal role of IgG1 in response against SARS-CoV-2, we hypothesized that common functional variants in the IGHG1 gene—either individually or synergistically with IGHG3 and FCGR2A—might modulate the extent of COVID-19 severity." (PMID 38602517, 2024). "The absence of a difference between the control group and the COVID-19 group, as well as the absence of a difference between COVID-19 patients and European FCGR2A allele frequencies, demonstrate that this gene is not related to disease severity." (PMID 37896870, 2023). "Therefore, CD40, FCGR2A and CASP3 genes are discussed as the genetic predisposition factors of KD, as well as severe COVID-19 and MIS-C, in children." (PMID 37896870, 2023). "A review study observed that variants in cytokine genes such as IL-1β, IL1R1, IL1RN, IL-6, IL-17A, FCGR2A, and TNF may be associated with disease susceptibility and/or severity, cytokine storm, and/or COVID-19 complications like thrombosis." (PMID 37662953, 2023). "Variants in cytokine genes such as IL1B, IL1R1, IL1RN, IL6, IL17A, FCGR2A, and TNF could be related to disease susceptibility and cytokine storm, and/or COVID-19 complications (e.g., venous thrombosis)." (PMID 33868239, 2021). "We performed a study using peripheral blood mRNA-seq data from 41 COVID-19 patients to obtain the immune-characterized genes of COVID-19 severe disease, namely, the hub genes (FPR1, FCGR2A, TLR4, S100A12, CXCL1, and LTF)." (PMID 38674681, 2024). "Based on the Degree, MCC, Closeness, Betweenness, and MNC algorithms of the CytoHubba plug-in, six genes (FPR1, FCGR2A, TLR4, S100A12, CXCL1, and LTF) were confirmed as hub genes related to COVID-19 severe." (PMID 38674681, 2024). "In the COVID-19 group, the TYK2 rs2304256, OAS1 rs10774671, CD40 rs4813003 and FCGR2A rs1801274 homozygote and heterozygote frequencies were in accordance with those indicated by the Hardy–Weinberg principle (p > 0.05)." (PMID 37896870, 2023). "Our research indicated that certain polymorphisms in the genes ACE2 rs2074192, IFNAR2 rs2236757, OAS1 rs10774671, OAS3 rs10735079, CD40 rs4813003, FCGR2A rs1801274 and CASP3 rs113420705 could predict cytokine responses in pediatric COVID-19 patients." (PMID 40066463, 2025). "In this study, we used mRNA-seq data from the peripheral blood of COVID-19 patients to identify six COVID-19 severe immune characteristic genes (FPR1, FCGR2A, TLR4, S100A12, CXCL1, and L TF), and found neutrophils to be the critical immune cells in COVID-19 severe disease." (PMID 38674681, 2024). "Within the network, we suspected that the 6 ceRNA subnetworks (i.e., MSTRG.119845.30/hsa-miR-20a-5p/TNFRSF1B, MSTRG.119845.30/hsa-miR-29b-2-5p/FCGR2A, and MSTRG.106112.2/hsa-miR-6501-5p/STAT3) may play a crucial role in the development of COVID-19." (PMID 33833618, 2021).
COVID-19 (continued). "The frequency of ACE2 rs2074192, IFNAR2 rs2236757, OAS3 rs10735079, FCGR2A rs1801274 and CASP3 rs113420705 genotypes did not follow the Hardy–Weinberg equilibrium (p < 0.05) due to the directional selection made in our study (focusing on patients with COVID-19)." (PMID 37896870, 2023).
breast carcinoma (15 papers, 2011 to 2025). "Mutations or deletions of FCGR2A can lead to significant resistance to immunotherapy in a variety of tumor types including colon cancer, breast cancer, and leukemia." (PMID 36717900, 2023). "For example, the trastuzumab mediated ADCC of anti-HER2 breast cancer cells is enhanced with FCGR2A-p.166His and FCGR3A-p.176Val, compared to the other alleles, and in case of neutrophil-mediated ADCC for FCGR2A-p.166His." (PMID 31632391, 2019). "This study was conceived to assess the effects of FCGR2A and 3A polymorphisms on pathological complete response (pCR) in breast cancer patients treated with trastuzumab-based neoadjuvant." (PMID 28983344, 2015). "Besides, polymorphisms in FCGR2A have been validated with high degree association of trastuzumab and cetuximab benefit in the adjuvant treatment of breast cancer and colorectal cancer." (PMID 36818162, 2023). "Furthermore, FCGR2A is reportedly associated with the pharmacodynamics of monoclonal antibodies in different cancer types, such as colorectal cancer, breast cancer, and metastatic squamous cell head and neck cancer." (PMID 31992246, 2020). "The H131R polymorphism of FCGR2A gene encoding FcγRIIA, (whose expression is restricted to myeloid cells), is associated with patient responses to rituximab (lymphoma), cetuximab (colon cancer), and trastuzumab (breast cancer)." (PMID 32117299, 2020). "Further, in a sample of 15 operable and 35 metastatic HER2-positive breast cancer patients, FCGR2A His/His predicted the response to trastuzumab in neoadjuvant chemotherapy and in metastatic setting, while FCGR3A Val/Val did not." (PMID 28983344, 2015). "The aim of the study was to validate the association between the Arg166His polymorphisms of the Fc immunoglobulin receptor 2A (FCGR2A) and the Val212Phe of FCGR3A and pathological clinical response (pCR) to trastuzumab in HER2-positive breast cancer patients." (PMID 28983344, 2015). "Similarly, in colon, prostate, and breast cancers, interference with FCGR2A has proven effective in limiting platelet activation." (PMID 41226816, 2025). "Indeed, patients carrying the allelic variants of FCGR2A, FCGR2C, and FCGR3A which exhibit increased affinity for human IgG demonstrated better responsiveness to anti-tumor antibody therapy in cases of B cell lymphomas, colorectal, renal, and breast cancers." (PMID 35372055, 2022). "Our data suggest that the results are robust in different NSCLC datasets and the key target genes identified (ITGA2B, FLNA, GRB2, FCGR2A, and APP, etc.)seem to also be strongly expressed in the breast cancer and pancreatic cancer datasets we analyzed." (PMID 41226816, 2025). "In HER2+ breast cancer, FCGRIA and FCGR2A were expressed on monocytes and macrophages, whereas in TNBC, FCGRIA and FCGR2A were expressed on monocytes, macrophages, and DCs." (PMID 41128663, 2025). "Several studies concerning FCGR polymorphisms and efficacy of trantuumab and rituximab demonstrated that FCGR2A H131R and FCGR3A V158F could predict clinical efficacy and survival of patients with breast cancer and lymphoma, respectively." (PMID 26363448, 2015). "The authors concluded that FCGR2A H131R and FCGR3A V158F genotype did not correlate with trastuzumab efficacy in HER2-positive breast cancer." (PMID 23286345, 2013).
Autoimmunity (8 papers, 2015 to 2025). The occurrence of an immune reaction against the organism's own cells or tissues. "The 99% credible set for this locus, which is associated not only with AS, but with a range of other autoimmune conditions, contained only six variants spanning 11kb of the promoter region and first 3 exons of FCGR2A." (PMID 26406328, 2015). "Specific genes involved in autoimmunity related to these processes, including immunoglobin-involved FCGR2A and complement C1QA, were plotted." (PMID 40428335, 2025). "Prior studies have demonstrated strong evidence that FCGR2A is not only involved in immune system activities but also with autoimmunity." (PMID 34646264, 2021).
melanoma (8 papers, 2018 to 2026). A malignant, usually aggressive tumor composed of atypical, neoplastic melanocytes. "FCGR2A was found to be positively associated with survival in melanoma patients." (PMID 36704353, 2022). "Importantly, multivariate Cox regression and survival curve analysis revealed that PDE3A and EPPK1 were negatively correlated with melanoma patient survival; however, FCGR2A was positively correlated with patient survival." (PMID 35664780, 2022). "In univariate Cox proportional hazard regression analysis, 3 of 11 genes (FCGR2A, PDE3A, and EPPK1) were significantly related to the prognosis of patients with melanoma." (PMID 35664780, 2022). "When combined with the results of univariate Cox proportional hazard regression analysis, 3 of 11 genes (FCGR2A, PDE3A, and EPPK1) were related to the prognosis of patients with melanoma." (PMID 35664780, 2022). "To determine pairwise correlations involving MYBL2 expression and three genes (FCGR2A, PDE3A, and EPPK1), we reanalyzed the transcriptome data of melanoma cases from TCGA." (PMID 35664780, 2022). "In summary, these results revealed that three key genes (FCGR2A, PDE3A, and EPPK1) may be potential prognostic factors in patients with melanoma." (PMID 35664780, 2022). "Importantly, we identified three key genes (FCGR2A, PDE3A, and EPPK1) that were correlated with the survival of melanoma patients." (PMID 35664780, 2022). "However, four genes, i.e., HPDL, GRIPAP1, GBP2, and TRIM34, have been reported to exhibit prognostic significance with respect to melanoma for the first time, while HAPLN3, CCL8, FCGR2A, and IFITM1 have been reported to relate with the initiation and immune microenvironment of cutaneous melanoma." (PMID 36818162, 2023).
ulcerative colitis (8 papers, 2016 to 2025). An inflammatory bowel disease involving the mucosal surface of the large intestine and rectum. "Genetic susceptibility to a higher FCGR2A level was linked to a reduced risk of ulcerative colitis, whereas a genetically predicted higher PAM level was associated with an increased risk of chronic ulcerative colitis." (PMID 40868097, 2025).
atherosclerosis (7 papers, 2010 to 2023). A disease characterized by the build-up of fatty material and calcium deposition in the arterial wall resulting in partial or complete occlusion of the arterial lumen. "The expression of FCGR2A on platelet surfaces is also increased in individuals with two or more risk factors for atherosclerosis and is more pronounced in patients with diabetes." (PMID 37268894, 2023). "After adjusting for the traditional risk factors for atherosclerosis in multivariate analysis, the only biomarker that remained significantly associated with APCA was FCGR2A." (PMID 37892617, 2023). "FCGR2A serves an essential role in atherosclerosis by combining with CRP, which leads to increased secretion of inflammatory cytokines, chemokines, and ROS." (PMID 32684073, 2020). "C-reactive protein (CRP) plays a critical role in atherosclerosis, and FCGR2A is its main receptor." (PMID 37268894, 2023). "While decreased FCGR2A expression has been reported to play a role in the pathogenesis of atherosclerosis, increased FCGR2A expression in platelets may also play a role in atherothrombosis." (PMID 33441605, 2021).
inflammatory bowel disease (6 papers, 2016 to 2025). A spectrum of small and large bowel inflammatory diseases of unknown etiology. "Further investigations will facilitate a deeper understanding of the precise mechanism by which FCGR2A contributes to the pathogenesis of inflammatory bowel disease, as well as explore its potential as a viable therapeutic target for enhancing patient clinical outcomes and quality of life." (PMID 39857814, 2025). "The KD-associated FCGR2A SNP (rs1801274; A/G, p.His167Arg, previously assigned as p.His131Arg) is associated with autoimmune diseases such as ankylosing spondylitis, SLE, inflammatory bowel disease (IBD), and KD." (PMID 34830213, 2021).
leukemia (6 papers, 2020 to 2023). A malignant (clonal) hematologic disorder, involving hematopoietic stem cells and characterized by the presence of primitive or atypical myeloid or lymphoid cells in the bone marrow and the blood. "Both FCGR2A and CD163 have been linked to lymphoma and leukemia; they have been studied as diagnostic and prognostic biomarkers." (PMID 37653176, 2023).
colorectal cancer (5 papers, 2011 to 2023). A primary or metastatic malignant neoplasm that affects the colon or rectum. "We have successfully replicated our previous results demonstrating an association between FCGR2A genotype and survival in wild‐type KRAS colorectal cancer patients treated with cetuximab." (PMID 30318772, 2018). "We analyzed the influence of 8 germinal polymorphisms of candidate genes potentially related to EGFR signalling (EGFR, EGF, CCND1) or antibody-directed cell cytotoxicity (FCGR2A and FCGR3A) on outcome of colorectal cancer (CRC) patients receiving cetuximab-based therapy." (PMID 22117530, 2011).
immune thrombocytopenia (5 papers, 2019 to 2025). "Curiously, we found the yet poorly explored gene FCGR2A (associated with transcript FCGR2A-201 found in our signature) as a predicted successful target for drugs such as SM-101 in non-cancer diseases like Idiopathic thrombocytopenic purpura, according to the Therapeutic Target Database (TTD)." (PMID 34316711, 2021). "In KD and in immune thrombocytopenia (ITP), it is indeed the case that the more activating variants (FCGR2C-ORF, FCGR3A-p.176Val, FCGR2A-p.166His) are associated with disease susceptibility." (PMID 31632391, 2019). "Finally, concerning immune thrombocytopenia, a meta-analysis ascertained an association between FCGR2A-p.166His and susceptibility to childhood ITP, but not adult ITP." (PMID 31632391, 2019).
influenza (5 papers, 2015 to 2022). An acute viral infection of the respiratory tract, occurring in isolated cases, in epidemics, or in pandemics; it is caused by serologically different strains of viruses (influenzaviruses) designated A, B, and C, has a 3-day incubation period, and usually lasts for 3 to 10 days. "Two SNPs in the C1QBP (rs3786054) and FCGR2A (rs1801274) genes have been reported to be associated with the cases of severe influenza in Mexico in 2009." (PMID 33766078, 2021). "Researchers studied the rs1801274 variant of the FCGR2A gene and concluded that this variant may be related to greater susceptibility to severe forms of flu." (PMID 33766078, 2021). "In the present study, the influence of the His131Arg (rs1801274) polymorphism, a variant of the FCGR2A gene, was investigated in 436 patients with a diagnosis of influenza A(H1N1)pdm09, evaluated at health services in the northern and northeastern regions of Brazil between June 2009 and August 2010." (PMID 27267995, 2016). "Several polymorphisms which have been known for the susceptibility to influenza infection include CD55, C1QBP, FCGR2A, IFITM3, TNF, RPAIN, LTA and KIR." (PMID 33766078, 2021). "Out of 11 SNPs in the vicinity of FCGR2A, only one had a nominally significant association with influenza severity (rs7551957, p = 0.0288), which did not survive Bonferroni correction." (PMID 26379185, 2015).
metastatic colorectal cancer (5 papers, 2013 to 2023). "We previously reported that the FCGR2A H/H genotype was associated with longer overall survival (OS) in cetuximab‐treated chemotherapy‐refractory patients with metastatic colorectal cancer." (PMID 30318772, 2018). "In conclusion, this analysis confirms that FCGR2A H/H polymorphism in patients with wild‐type KRAS metastatic colorectal cancer treated with cetuximab is associated with significantly longer OS without affecting toxicity profiles." (PMID 30318772, 2018). "FCGR2A polymorphisms are correlated with metastatic colorectal cancer." (PMID 38155938, 2023). "Most studies have been limited by small samples sizes and have reported inconsistent associations between the FCGR2A and the FCGR3A polymorphisms and clinical outcome in metastatic colorectal cancer (mCRC) patients treated with cetuximab." (PMID 24884501, 2014). "However, it provides further insight into the mechanistic role of FCGR polymorphisms in clinical outcomes of cetuximab‐treated, metastatic colorectal cancer, namely, the role of FCGR3A polymorphism in modifying the primary relationship between FCGR2A and clinical outcomes." (PMID 30318772, 2018).